ARID1A (AT-rich interaction domain 1A)
Diseases named in the same sentence as ARID1A in open-access papers (continued):
Sharing a sentence is not in itself a finding about the gene and the disease.
cancer (continued). "Here, we will highlight the progress made in identifying therapeutic targets for ARID1A mutant cancers." (PMID 34671561, 2021). "Although EYS has not previously been investigated in the context of prognosis, the adverse prognostic impact of APC, NOTCH1, ARID1A, and filamin A has been reported in other cancer types." (PMID 33801954, 2021). "To address the clinical relevance of targeting mitochondrial function as a potential therapeutic strategy for the treatment of ARID1A-deficient OCCC cancers, we tested the ability of IACS-010759 to suppress the growth of ARID1A-deficient OCCC tumors in vivo." (PMID 33947138, 2021). "Overall, ARID1A is the most frequently mutated SWI/SNF subunit in different cancer types; however, PBRM1 mutations are much more common in ccRCC than ARID1A mutations." (PMID 33419967, 2021). "Compared with normal adjacent tissues, the protein level of ARID1A in cancer tissues was obviously reduced (p<0.01)." (PMID 33592583, 2021). "Other mutated cancer genes included those involved in Wnt signaling (APC, AMER1), mitogen signaling (KRAS, BRAF), epigenetic modification (ARID1A, ARID2, DNMT3A, NCOA3) and DNA repair (RAD50, BRIP1, ERCC5, RECQL4)." (PMID 33776923, 2021). "MFUM-BrTNBC-1 has a stop-mutation in the ARID1A gene (an SWI/SNF chromatin remodelling gene), which is commonly mutated in cancer (including in MCF-7 and MDA-MB-231 CLs)." (PMID 35011679, 2021). "We found a rather narrow range of other genes (KMT2D, FBXW7, GNAS, ARID1A, NF1 and CTNNB1) harbouring mutations in 6–12% of the patients and a long tail of cancer genes with mutations in <6%." (PMID 34647903, 2021). "Subsequently, research on cancer whole-exome high-throughput sequencing has revealed frequent mutations of genes encoding multiple subunits of the SWI/SNF complex, among which ARID1A is the most frequently mutated." (PMID 34671561, 2021). "ARID1A, an SWI/SNF chromatin-remodeling gene, usually is mutated in cancer and is considered to be capable of suppressing tumors." (PMID 33771191, 2021). "One of the therapeutic paradigms explored in ARID1A mutant cancers is synthetic lethality, which refers to the lethal effect of the simultaneous alteration of two genes which, when individually perturbed, do not impair cell viability." (PMID 33741974, 2021). "Here we find that a gene called ARID1A, which is frequently lost in cancer cells, prevents such collisions between replication and transcription machinery." (PMID 33826602, 2021). "ARID1A is part of the SWI/SNF complex, a subfamily of ATP-dependent chromatin remodeling complexes, and is mutated in about 20% of all cancers across entities." (PMID 34200508, 2021). "A pan-cancer analysis of ARID1A alterations recently highlighted their important value as predictive biomarkers for immunotherapy." (PMID 33315149, 2021). "Collectively, these findings manifest that compartment switching induced by Arid1a depletion modulates the transcription of some cancer-related genes, such as Pmp22, Atg10, Gsc, Rnf125, and Cdh5, which have been known to be involved in tumorigenesis." (PMID 34689165, 2021). "Another study on ARID1A-mutant cancer showed that HDAC2 and PRC2/EZH2 co-repressed the expression of apoptosis-promoting protein PIK3IP1." (PMID 33941852, 2021). "The up-regulation of phosphorylated AKT was observed in cancer cell silencing of ARID1A activation, and restoration of ARID1A inhibited cell proliferation and induced apoptosis." (PMID 34217266, 2021). "However, molecular consequences of ARID1A deficiency in cancer may be exploited therapeutically." (PMID 33608032, 2021). "SWI/SNF subunits are the most commonly mutated chromatin-regulatory complexes in human cancer, mutated in 19.6% cancers, with subunits ARID1A, PBRM1, SMARCA4, and ARID2 already part of routine cancer diagnostics." (PMID 34944438, 2021).
cancer (continued). "Previous studies had demonstrated the essential role of ARID1A in carcinogenesis and cancer development." (PMID 34715776, 2021). "Nevertheless, due to functional redundancy at enhancers, ARID1B is remarkably essential in ARID1A-deleted cancers." (PMID 34070411, 2021). "We found that somatic genomic alterations of the RECQL4, JAK3, ARID1A, and MAGI1 genes, combined with MBs, were associated with the development of metachronous cancers after curative ESD and successful HP eradiation." (PMID 33328548, 2020). "Compared to other common cancer types, GCTs show high ARID1A expression (7th place of the 37 analyzed cancer types)." (PMID 32272809, 2020). "The appearance of these highly ranked aberrant signaling nodes was plausible, since other autochthonous models have also reported upregulation of EMT-associated genes and MYC activation within the resulting Arid1a-null cancers." (PMID 32967217, 2020). "Mutations in ARID1A have been found in several cancers, and SWI/SNF-associated gene mutations occur in approximately 20% of all malignancies, whereas the most frequent mutations in ARID1A are found in OCCC (46–57%) and EnOC (approx. 30%)." (PMID 32455595, 2020). "Since aberrant methylation plays a key role in regulating ARID1A expression in several cancers, we examined the methylation status of the ARID1A promoter in the six CRC cell lines by methylation specific PCR (MSP)." (PMID 32334542, 2020). "The bioinformatic analyses in this research indicated that ARID1A or ARID1B mutations were associated with instability in the cancer cell genome and cancer mutability, as indicated by the elevated TMB, which is a proven biomarker for cancer immunotherapy." (PMID 32791957, 2020). "Mammalian SWI/SNF complexes are composed of 12–15 subunits, and mutations in subunit genes including ARID1A, SMARCA4, ARID1B, ARID2, and PBRM1 occur across a wide spectrum of human cancers." (PMID 33381446, 2020). "Loss of ARID1B in ARID1A-deficient backgrounds destabilizes SWI/SNF complexes and impairs cancer and primary cell proliferation." (PMID 33381446, 2020). "Several ERGs had the highest mutation frequency repeatedly in many cancer types, namely the KMT2C/D family (seven cancers), ARID1A (five cancers), BAP1 (three cancers), and ATRX (three cancers)." (PMID 32963031, 2020). "While NGS analysis unveiled common mutations in PTEN, CTNNB1, and ARID1A, different PIK3CA and PIK3R1 mutations were also detected, suggesting the existence of at least two cancer clones." (PMID 32652986, 2020). "This indicates that the presence of ARID1B is necessary for stabilizing the SWI/SNF complex in ARID1A-mutant cancer cells." (PMID 32245111, 2020). "Collectively, our findings highlight the important value of ARID1A alterations as pan-cancer predictive biomarkers for ICI treatment." (PMID 31949479, 2020). "We found a relatively high frequency (6.2%) of ARID1A alterations and significant predictive value for ICIs treatment in >40,000 patients with cancers." (PMID 31949479, 2020). "In this study, we performed this pan-cancer analysis by using online database to systematically characterize the prevalence and predictive value of ARID1A alterations across multiple cancer types." (PMID 31949479, 2020). "Inactivation of ARID1A is thought to activate cell cycle progression, thereby contributing to uncontrolled cellular proliferation in cancer cells." (PMID 33344089, 2020). "To functionally address this paradox, we revisited the role of ARID1A loss in multistep pancreatic carcinogenesis using GEM model and its direct cellular functions in cancer cells." (PMID 32967217, 2020). "A combination trialof 1 and 11 in participants with gynecologicalcancers with ARId1Aloss or no loss, to assess response rates in groups of participantsselected based on their cancer cell subtype and the presence of anabnormality in ARID1A gene." (PMID 33135887, 2020).
cancer (continued). "The current evidence suggested that ARID1A alterations would yield promising predictive value for ICI treatment across diverse cancers." (PMID 31949479, 2020). "A wide range of cancer-gene mutations are detected by NGS and loss of function mutations in the ARID1A is detected repeatedly and frequently in various cancer types." (PMID 32334542, 2020). "Among the non-synonymous mutations, 33 were present in both cell line and primary tumor, including truncating mutations of ARID1A and ARID1B genes and a cancer hotspot missense mutation of DICER1 gene (p.D1810Y)." (PMID 33052929, 2020). "The SWI/SNF chromatin remodeling complex has attracted increasing attention, particularly in cancer biology due to mutations, deletions and insertions in BRG1, and in some of the SWI/SNF core subunits (e.g., SNF5, ARID1A) in ~20% of human tumors." (PMID 32033115, 2020). "ARID1B, a structurally related but mutually exclusive homolog of ARID1A in the SWI/SNF chromatin-remodeling complex, is a potential synthetic lethal vulnerability in ARID1A-mutant human cancers." (PMID 32967217, 2020). "The ARID1A DNA methylation profile of GCT cell lines mimicked the profile found in the TCGA pan-cancer cohort." (PMID 32272809, 2020). "ARID1A or ARID1B mutations and the resultant functional deficiencies are tightly associated with cancer mutability, PD-L1 expression and TIME modulation and are associated with a good prognosis for ICIs treatment." (PMID 32791957, 2020). "Additional subclonal mutations in ARID1A and in other SWI/SNF-complex members evolved during cancer progression, indicating a role of SWI/SNF-complex modulation during carcinogenesis and cancer progression." (PMID 31949146, 2020). "We analyzed the expression of ARID1A in various cancers (including GCTs) by screening microarray data of GCT tissues and cell lines as well as the ‘The Cancer Genome Atlas’ (TCGA) pan-cancer dataset." (PMID 32272809, 2020). "Data on genetic alterations in seromucinous carcinoma are limited, although one international study showed mutations in ARID1A, KRAS, PIK3CA, and PTEN in 16%, 70%, 37%, and 19% of seromucinous carcinoma, respectively, based on analysis of 32 cases." (PMID 32023964, 2020). "Compared with ARID1A wild-type tumors, ARID1A-mutated tumors display significantly less genomic instability as measured by CNA across multiple cancer types." (PMID 31492885, 2019). "In vitro knockdown of wt ARID1A/re-expression of clinically relevant mutant ARID1A studies in cancer cell lines and ES cells demonstrated that ARID1A’s effect on the proliferation of normal ovarian surface epithelial cells." (PMID 31731647, 2019). "In future studies, it will be very interesting to decipher at which time point during transformation cancer cells lose ARID1A expression." (PMID 31217031, 2019). "Other novel, highly scoring gene pair predictions that included cancer associated genes included PARP1 with PBRM1, BRCA2, ARID1A and APC as well as PIK3CA with MAP2K1, ABL1 and EGFR." (PMID 30995217, 2019). "Another gene known to functionally link alterations in metabolism in cancer cells to a vulnerability to alterations in redox metabolism is ARID1A." (PMID 31434226, 2019). "The tumor suppressor gene ARID1A has a high mutation rate in GI cancers and its deficiency is correlated with the microsatellite instability (MSI) genomic feature of cancer." (PMID 31277418, 2019). "Taken together, our work significantly expands the knowledge about the context-dependent functions of ARID1A in cancer." (PMID 31217031, 2019).
cancer (continued). "Loss of ARID1A shortens time to cancer-specific mortality in men, where mutations are associated with both sporadic and hereditary MSI cancers." (PMID 31581674, 2019). "Immunohistochemical expression of HDAC6, hypoxia inducible factors-1α (HIF-1α), programmed death-1 ligand (PD-L1), CD44 (cancer stem cell marker), and ARID1A was analysed for 106 OCCC patients." (PMID 30787326, 2019). "Here, we report that ARID1A is regulated by human antigen R (HuR), an RNA-binding protein that is highly expressed in a wide range of cancers and enables resistance to chemotherapy and radiation." (PMID 31847141, 2019). "Conversely, ARID1A deficiency correlated with MSI genomic signature, and increased mutation load across multiple human cancer types." (PMID 30866995, 2019). "Besides the elevated antitumor immune signatures, ARID1A-mutated GI cancers exhibited significantly higher PD-L1 expression levels than ARID1A-wildtype GI cancers that would enhance the immunotherapy response and accordingly result in a better survival prognosis in this cancer subtype." (PMID 31277418, 2019). "Inactivation of the chromatin-remodelling factor AT-rich interactive domain-containing protein 1A (ARID1A) is found at high frequency in multiple cancer types and it is thought to promote tumorigenesis by interfering with DNA repair, like ROS-induced DSBs." (PMID 31426306, 2019). "The APC mutant clone had also developed an ARID1A mutant subclone (ARID1A detected in a single region of carcinoma)." (PMID 29991641, 2019). "ARID1A and ARID1B are the only known DNA-binding proteins in the SWI/SNF-A complex; inactivation of ARID1B in an ARID1A-deficient background can disrupt SWI/SNF complex activity, thereby contributing to the development and progression of human cancers." (PMID 29890703, 2018). "This suggests that the presence of ARID1B is essential for stabilizing the SWI/SNF complex in ARID1A-mutant cancer cells." (PMID 29890703, 2018). "A second set consisted of an additional 15 cancer-related genes (Nf1, Mki67, Mllt4, Fgfr2, Ctnnb1, Fat1, Clp1, Fat4, Arid1a, Nat1, Nat2, Setd2, Impg1, Nbas and Npat)." (PMID 29925311, 2018). "Most interestingly, tumors with ARID1A mutations acquire sensitivity to pan-HDAC inhibitors, thus making ARID1A-bearing cancers attractive for HDAC-based therapy." (PMID 30200265, 2018). "KEGG analysis of ARID1A/1B targets revealed enrichment in Pathways in Cancer, with specific identification of Adherens junction, Ras/Rap1 signaling pathway, ECM-receptor interaction, PI3K-AKT signaling pathway, and ErbB signaling pathway." (PMID 28967863, 2017). "Somatic mutations of potential driver genes such as ARID1A, ATM, and MTOR promoted cancer growth, and many mutations were generated due to MMR deficiency." (PMID 28974240, 2017). "Besides germline BRCA1/2-mutant cancers, there has been increasing evidence that PARP inhibitors may have a role in somatic BRCA1/2-mutant cancers, or cancers associated with HR deficiency, and more recently, possibly even tumors deficient in chromatin regulation like cancers with ARID1A mutations." (PMID 28829366, 2017). "Truncating mutations in SWI-SNF cancer genes, including ARID1A and ARID2, emerged in three of five cancers relapsing after taxane chemotherapy." (PMID 28810143, 2017). "Frequent mutation of ARID1A has been shown in HCC, provoking cancer progression and metastasis by epigenetic alteration." (PMID 28038442, 2017).
cancer (continued). "We analyzed the Genomics of Drug Sensitivity in Cancer (GDSC) database and found that ARID1A-mutant cancer cell lines were more sensitive to the ROS-inducing agent elesclomol than were ARID1A-wildtype cancer cell lines." (PMID 27486766, 2016). "Treatment with elesclomol at 10 and 20 nM also induced apoptosis more potently in ARID1A-mutant cancer cells than in ARID1A-wildtype cancer cells (P = 0.0227 and P = 0.0057, respectively)." (PMID 27486766, 2016). "To identify drug targets for ARID1A-mutant cancer cells, we analyzed the publicly available GDSC drug database and compared the drug sensitivities of ARID1A-mutant and ARID1A-wildtype cancer cell lines." (PMID 27486766, 2016). "Here, the authors demonstrate that defects of ARID1A and other subunits sensitizes cancer cells to the DNA checkpoint kinase inhibitor ATR in a synthetic lethal manner." (PMID 27958275, 2016). "By analyzing the Genomics of Drug Sensitivity in Cancer database, we found that ARID1A-mutant cancer cell lines were more sensitive to treatment with the reactive oxygen species (ROS)-inducing agent elesclomol." (PMID 27486766, 2016). "The post-treatment cancer retained its pathogenic CDKN2A and SMARCA4 mutations and gained a low VAF, truncating ARID1A change." (PMID 27045317, 2016). "We found that the ARID1A-mutant cancer cell lines had significantly lower IC50s of elesclomol than did the ARID1A-wildtype cancer cell lines (P = 0.034)." (PMID 27486766, 2016). "Taken together, these results demonstrated that ARID1A-mutant cancer cell lines are more sensitive to treatment with elesclomol." (PMID 27486766, 2016). "The transcriptional mechanism of ARID1A would be addressed to deal with the heterogeneity of different cancers and physiological and pathological variations." (PMID 27323812, 2016). "ARID1A is located within chromosomal region 1p36, a region frequently deleted in a variety of human cancers." (PMID 26378916, 2015). "Only all-cause mortality seemed to be partially affected by differences in low-grade tumors between ARID1A+ and ARID1A− as well as by different cancer types, i.e., gastrointestinal/gynecological vs. urological cancers." (PMID 26384299, 2015). "Compared to ARID1A+, ARID1A− significantly increased cancer-specific mortality (studies = 3; RR = 1.55, 95% confidence interval (CI) = 1.19–2.00, I2 = 31%)." (PMID 26384299, 2015). "MSI involves short repeats of mono- or oligonucleotides that are typically also present in ARID1A, and MSI is associated with a remarkably high rate of sequence mutation in cancer cells." (PMID 26384299, 2015). "The region contains multiple genes with a known or suspected role in cancer including ARID1A, E2F2, NBPF1, PAX7, RUNX3 and SDHB." (PMID 25420937, 2014). "ATRX, ARID1A, PBRM1, and SMARCA4 are also among the most frequently mutated chromatin factors in cancer, and are all components of the chromatin remodeling complex SWI/SNF, which has been shown to facilitate double-strand break repair." (PMID 25484917, 2014). "The results of this study demonstrate an interdependency of ARID1A and the PI3K/AKT pathway, which results in significantly increased sensitivity of ARID1A-deficient cancer cells to PI3K- and AKT- inhibition." (PMID 24979463, 2014). "Despite the apparent high frequency of ARID1A mutations from the TCGA database in some primary tumors such as pancreatic (8.8%), stomach (7.3%), and endometrial (44.4%), BAF250 was initially noted to be infrequently silenced in cancer cell lines." (PMID 25774356, 2014).